TXN (thioredoxin)
Diseases named in the same sentence as TXN in open-access papers (continued):
Sharing a sentence is not in itself a finding about the gene and the disease.
lung carcinoma (continued). "Given the important roles of antioxidant enzymes such as mitochondrial superoxide dismutase (SOD) and thioredoxin (TXN) in modulating intracellular ROS balance, we decided to determine if RV treatment affects the expression of SOD and TXN in lung cancer cells." (PMID 23533664, 2013). "The proportion of cells positive for TXN was higher in lung cancer tissues." (PMID 36776308, 2023). "High expression of TXN plays an important role in lung cancer development and prognosis." (PMID 36776308, 2023). "The proliferation ability was attenuated after knockdown of TXN and was enhanced after overexpression of TXN, suggesting that TXN could promote the proliferation of lung cancer." (PMID 36776308, 2023). "Because it is a prospective prognostic factor, targeting TXN may have clinical benefits in the treatment of lung cancer." (PMID 36776308, 2023). "Evaluation of the TCGA dataset and the five GSE datasets found that TXN expression was higher in tumor than in normal tissues, consistent with previous findings, indicating a correlation between high TXN expression and lung cancer." (PMID 36776308, 2023). "Following identification of TXN as an optimal differentially expressed gene by bioinformatics, the prognostic value of TXN in lung cancer was evaluated by univariate/multivariate Cox regression and Kaplan–Meier survival analyses, with validation by receiver operation characteristic curve analysis." (PMID 36776308, 2023). "This study evaluated the role of TXN in lung cancer by bioinformatics analyses." (PMID 36776308, 2023). "In addition to being an important biomarker of oxidative stress, the present study utilized bioinformatics to identify TXN as a molecular target of oxidative stress in lung cancer by mining of genes related to both lung cancer and oxidative stress." (PMID 36776308, 2023). "The overexpression of TXN in lung carcinomas and the subsequent redox regulation and activation of a number of intracellular proteins that control cell growth and proliferation may be an indication of more aggressive tumor phenotypes." (PMID 32756515, 2020). "Similarly, it was shown that simultaneous inhibition of TXN and glutathione systems resulted in synergistic killing of lung cancer cells." (PMID 24342878, 2013). "TXN may be a tumor-suppressing therapeutic target in lung cancer." (PMID 36776308, 2023). "The results showed that the expression of TXN and TXNRD1 was higher in most lung cancer cell lines than in the normal lung epithelial cell line Beas-2b, while the opposite was observed for TXNIP." (PMID 39744566, 2025). "The proteins TXN and PPIA (Cyclophilin A) were up-regulated in lung cancer BALs as compared to the other groups." (PMID 23389041, 2013). "In lung cancer, 9 genes correlated with poor prognosis, including GCLC, NAD(P)H dehydrogenase (quinone) 1 (NQO1) and thioredoxin (TXN), and 1 with good outcome." (PMID 24342878, 2013). "siRNA-mediated knockdown of TXN and TXNRD1 inhibited cell proliferation of lung cancer cells." (PMID 39744566, 2025). "GSEA analysis in the present study showed enrichment of the MYC target, suggesting that TXN may target the MYC protein through the MAPK signaling pathway, promoting the occurrence and development of lung cancer." (PMID 36776308, 2023). "Here, the authors identify that thioredoxin (Trx) system inhibition mediates sensitivity to CHK1 inhibitor via regulating the activity of ribonucleotide reductase, demonstrating the synergistic effect of CHK1 inhibitor and inhibitors targeting Trx system in lung cancer models." (PMID 38821952, 2024). "The specific mechanisms of action of TXN in lung cancer have not been determined." (PMID 36776308, 2023). "Univariate Cox regression analysis showed that age (P = 0.022), T stage (P < 0.001), N stage (P < 0.001), M stage (P < 0.001), pathologic stage (P < 0.001), curative outcome (P < 0.001) and TXN expression (P = 0.024) were prognostic of survival in lung cancer patients, whereas gender was not." (PMID 36776308, 2023).
Hyperglycemia (17 papers, 2007 to 2022). An increased concentration of glucose in the blood. "In this study, hyperglycemia induced by STZ inhibited the thioredoxin antioxidative role, while glimepiride or both doses of D. saline treatment elicited upregulation of Trx activity in rat brain compared with the STZ group." (PMID 31998774, 2020). "Both studies reported that thioredoxin administration was able to overcome hyperglycemia-induced HIF-1α reduction and upregulated HIF-1α levels, which eventually enhanced wound healing by increasing blood supply to the wound site." (PMID 30654793, 2019). "TXNIP is a member of the alpha arrestin protein family that regulates and binds to reduced thioredoxin (TXN) and can be induced in response to oxidative stress, calcium influx and hyperglycemia." (PMID 30670947, 2018). "Overexpression of Txnip increases oxidative stress, while Txnip gene silencing restores thioredoxin activity in hyperglycemia." (PMID 24834056, 2014). "Hyperglycemia inhibits thioredoxin ROS-scavenging function through induction of thioredoxin-interacting protein (Txnip), which interacts with thioredoxin and serves as an endogenous inhibitor." (PMID 24834056, 2014). "We have previously shown that hyperglycemia regulates thioredoxin (TRX) activity-reactive oxygen species (ROS) through induction of thioredoxin-interacting protein (TXNIP) in metastatic breast cancer-derived cells MDA-MB-231." (PMID 21910912, 2011). "Hyperglycaemia in response to oral glucose impairs pancreatic B-cell function with decreasing thioredoxin levels." (PMID 17257277, 2007). "The effects of beverages containing catechin (615 mg/350 ml) per day for 4 weeks on postprandial hyperglycaemia and oxidative stress in healthy postmenopausal women lowered postprandial glucose levels (3%) and serum postprandial thioredoxin (5%) compared to the placebo group." (PMID 34867384, 2021). "Therefore, TXNIP may be induced via hyperglycemia regulated thioredoxin-ROS activity in Her-1/2 signaling pathway." (PMID 25605021, 2015). "Hyperglycemia activates the NLRP3 inflammasome, accompanied by TXNIP activation, which inhibits the expression of thioredoxin." (PMID 33637069, 2021). "Long-term hyperglycemia exerts the deleterious effects through overproduction of ROS that outweighs their degradation by antioxidant defense systems such as superoxide dismutase (SOD), catalase (CAT), heme oxygenase-1 (HO-1), and thioredoxin (Trx)." (PMID 25525607, 2014).
prostate carcinoma (12 papers, 2010 to 2026). A carcinoma that arises from epithelial cells of the prostate gland. "A label-free protein expression approach was used to assess the glutathione-thioredoxin antioxidative pathway in a prostate cancer cell line (PC-3) after exposure to gold nanoparticles conjugated with a targeting moiety (transferrin)." (PMID 37627612, 2023). "On the other hand, the treatment of prostate cancer cells with natural bioactive compounds reduces TXN expression, collaborating with the apoptosis of these cells." (PMID 33049715, 2020). "This review covers the possible roles of two ROS-induced transcription factors, Nrf1 and Nrf2, and the antioxidant proteins peroxiredoxin-1 (Prx-1) and Thioredoxin-1 (Txn-1) in modulating AR expression and signaling in aggressive prostate cancer (PCa) cells." (PMID 24281119, 2010). "Relatively few studies have been conducted on the thioredoxin system and prostate cancer, and while this system appears to play an important role in prostate cancer, the extent to which this system affects prostate cancer development and progression in humans remains uncertain." (PMID 26357575, 2015). "Interestingly, we found high expression of antioxidant genes; SOD1, TXN, LAMTOR5, and ATOX1 in prostate cancer patients having higher ERG fusion expression." (PMID 35508713, 2022). "While the clinical implications of these findings regarding prostate cancer is not clear, these results may reflect a compensatory response to redox imbalance, since the thioredoxin system is upregulated in prostate cancer." (PMID 26357575, 2015). "The binding activity of the nanodevice to the epithelial cells as well as the stroma of BPH was undetectable suggesting that the targeted thioredoxin proteins are not present in nonreactive stroma, and that the nanodevice is specifically binding to reactive stroma present in prostate cancer." (PMID 23762225, 2013).
Sepsis (12 papers, 2019 to 2025). Sepsis is defined as life-threatening organ dysfunction caused by a dysregulated host response to infection. "Although this study has revealed the diagnostic value of DPP4 and TXN in sepsis and their correlation with immune infiltration through bioinformatics methods, the specific molecular mechanisms still require further experimental validation." (PMID 40124361, 2025). "Based on three machine learning algorithms, we screened three potential biomarkers (NLRC4, S100A9 and TXN) and constructed a diagnostic model for sepsis." (PMID 40028203, 2025). "The upregulation of TXN has been verified to be significantly associated with inflammation in sepsis patients." (PMID 40028203, 2025). "Similarly, TXN was identified as a candidate diagnostic gene for sepsis-induced acute respiratory distress syndrome in a study focused on key iron death genes." (PMID 40124361, 2025). "Expression validation revealed that DPP4 was predominantly highly expressed in the control group, while TXN exhibited elevated expression in the sepsis group." (PMID 40124361, 2025). "MR analysis suggested that a decrease in GSTO1 levels is associated with an increased risk of sepsis, and that sepsis influences the levels of S100A9, TXN, and GSTO1." (PMID 40108736, 2025). "In sepsis, TXN exerts protective effects by mitigating oxidative stress and modulating inflammatory responses." (PMID 40861493, 2025). "TXN was also expressed in a variety of cell types, with higher expression in B cells in the sepsis group than in the control group." (PMID 40108736, 2025). "Although we have validated the upregulation of NLRC4, TXN, and S100A9 expression in the peripheral blood of sepsis patients through qRT-PCR, there are still some deficiencies, such as limited number of enrolled patients and the lack of multicenter validation." (PMID 40028203, 2025). "DPP4 and TXN were identified as key biomarkers, showing higher expression in control and sepsis samples, respectively." (PMID 40124361, 2025). "It has also been proved that sepsis affects the levels of S100A9, TXN and GSTO1 from the perspective of genetics, but the underlying mechanism is still unclear and needs to be further verified by basic experiments." (PMID 40108736, 2025). "DPP4 and TXN were validated as biomarkers for sepsis, with insights into immune infiltration and therapeutic potential at the single-cell level, offering novel perspectives for sepsis treatment." (PMID 40124361, 2025). "In conclusion, TXN has emerged as a central or key gene in sepsis research, consistently showing significant upregulation in sepsis samples, aligning with the findings of this study." (PMID 40124361, 2025). "In the validation datasets of GSE28750, GSE57065, GSE13904, GSE26378 and GSE26440, the expression of NLRC4, S100A9 and TXN were also significantly higher in the sepsis group." (PMID 40028203, 2025). "Through bioinformatics approaches, this study successfully identified five genes (IRAK3, S100A9, TXN, NFATC2, and GSTO1) associated with programmed cell death in the context of sepsis." (PMID 40108736, 2025). "Inhibiting TXNRD1 maintains TXN in its oxidized state, restricting Caspase-11 activation and alleviating sepsis." (PMID 39744566, 2025). "In conclusion, VDAC1, HSPA8, SOD1, HSPA9, TXN, and SNCA have been identified as oxidative stress-related genes associated with sepsis-induced ALI." (PMID 40694561, 2025). "Previous studies have suggested that TXN is a key regulator in maintaining endoplasmic reticulum (ER) homeostasis in sepsis." (PMID 40861493, 2025). "The results showed that the expression of NLRC4, S100A9 and TXN was significantly higher in sepsis patients." (PMID 40028203, 2025). "Although TXN exhibits significant upregulation in sepsis and its inhibition can reduce endoplasmic reticulum stress in cardiomyocytes, its primary function is localized intracellularly rather than being secreted into the bloodstream." (PMID 40694561, 2025).
Sepsis (continued). "The expression of IRAK3 and TXN in the control group, mild sepsis group and severe sepsis group increased in a gradient manner." (PMID 40108736, 2025). "Because TXN was significantly upregulated in sepsis and had a good AUC in the training and validation sets, we also observed the effect of interfering TXN on ER stress after LPS stimulation." (PMID 37346041, 2023). "Expression analysis of four diagnostic biomarkers suggested that the sepsis samples in cluster A had higher expression of SET, LPIN1, and CD74; however, the expression of TXN was remarkably higher in cluster B." (PMID 37346041, 2023). "The results of molecular biological experiments in vitro and in vivo further support the fact that TXN is a key player in maintaining ER homeostasis in sepsis." (PMID 37346041, 2023). "Through PCR analysis, it was found that levels of CD74, LPIN1, and SET were significantly decreased after sepsis in rats, whereas the level of TXN was significantly increased after sepsis in rats, which was consistent with the results of bioinformatics." (PMID 37346041, 2023). "The expression profiles of SET, LPIN1, and CD74 were significantly lower in the sepsis patients, whereas the expression of TXN was much higher." (PMID 37346041, 2023). "Another supportive fact for our study was that the mRNA expression levels of CD74, LPIN1, and SET were downregulated in rats with sepsis, whereas TXN was upregulated." (PMID 37346041, 2023). "Four ERRGs, namely SET, LPIN1, TXN, and CD74, have been identified as characteristic diagnostic biomarkers for sepsis." (PMID 37346041, 2023). "The biological experiments in vitro and vivo demonstrate TXN is emerging as crucial player in maintaining ER homeostasis in sepsis." (PMID 37346041, 2023). "In the training and test cohorts, we observed that the expression profiles of SET, LPIN1, and CD74 were significantly higher in the healthy group, whereas the expression of TXN was much higher in the sepsis group." (PMID 37346041, 2023). "This further supports previous results from our lab showing that the thioredoxin-null mutant can act as a live vaccine in a sepsis model of infection." (PMID 31265467, 2019). "Our results also indicated that TXN was a potential biomarker for sepsis." (PMID 40028203, 2025). "The expression of NLRC4, S100A9 and TXN was significantly higher in the sepsis patients." (PMID 40028203, 2025). "The nomogram illustrates the individual contributions of the five genes (TXN, MAPK14, WIPI1, CD82, and NEDD4) and clinical information (age, gender) to the overall risk score, providing a practical tool for estimating the probability of sepsis." (PMID 40299574, 2025). "For instance, by detecting decreased DPP4 concentrations or increased TXN concentrations in patient sera, combined with clinical scores [such as the Sequential Organ Failure Assessment (SOFA) score], the early diagnostic efficiency for sepsis can be enhanced." (PMID 40124361, 2025). "Two biomarkers, DPP4 and TXN, were identified and validated in the context of sepsis." (PMID 40124361, 2025). "Therefore, we plan to directly verify the roles of DPP4 and TXN in the pathogenesis of sepsis through gene knockout or overexpression experiments in the future and to explore their specific molecular mechanisms." (PMID 40124361, 2025). "The upregulation of TXN during sepsis may represent a compensatory mechanism to counteract excessive oxidative stress and inflammation." (PMID 40861493, 2025). "High expression of TXN may accelerate T-cell dysfunction by promoting oxidative damage, which is consistent with the high TXN expression observed in the sepsis group in this study." (PMID 40124361, 2025). "PCR analysis and western blotting were used to demonstrate the potential role of TXN in sepsis." (PMID 37346041, 2023).